INS (insulin)
Diseases named in the same sentence as INS in open-access papers (continued):
Sharing a sentence is not in itself a finding about the gene and the disease.
diabetes (continued). "One of the possible mechanisms which explains this inverse association between diabetes and PC, is the low insulin concentration in long-term diabetes, resulting in lower plasma IGF-1 levels in diabetics compared to non-diabetics." (PMID 33921222, 2021). "As an endogenous insulin sensitizer secreted by adipose tissue, reduction of adiponectin is an independent risk factor for hyperlipidemia and diabetes." (PMID 34040579, 2021). "Physical activity can effectively reduce the risk of diabetes, and an appropriate increase in energy consumption can effectively regulate postprandial insulin secretion and improve the glucose metabolism status." (PMID 34774072, 2021). "A quantitative deficiency of normally functioning insulin-producing pancreatic beta cells is a major contributor to all common forms of diabetes." (PMID 34335466, 2021). "A shared hallmark of both major forms of diabetes is a reduction in function (insulin secretion) or mass (cell number) of the pancreatic islet beta-cell." (PMID 35098034, 2021). "These physiological and metabolic changes confirmed decreased insulin sensitivity and impaired glucose tolerance associated with the development of type 2 diabetes mellitus." (PMID 34803926, 2021). "In type 2 diabetes (T2D), representing approximately 90% of the diabetes cases, patients present a loss of β-cell function and/or a resistance of the target tissues (liver, muscle and adipose tissue) to insulin action." (PMID 34040585, 2021). "Exercise causes increased sensitivity to insulin and is a very important part of treatment for all individuals who have diabetes." (PMID 34828602, 2021). "As the disease progresses, these cells lose the ability to secrete large amounts of insulin to maintain balance and the individual develops a deficiency of this hormone." (PMID 34366888, 2021). "In this report, we identified a novel nonsense INS mutation PPI-R46X associated with early-onset diabetes in two unrelated patients." (PMID 35069438, 2021). "A study has shown that increased HbA1c was related to compromised early-phase insulin secretion relatively compared to the insulin resistance in Koreans which were at high risk of diabetes." (PMID 33490287, 2021). "Diabetes is mainly manifested by absolute or relative deficiency of insulin and decreased sensitivity of target cells to insulin." (PMID 34987478, 2021). "Diabetes mellitus (DM) is a chronic metabolic disease characterized by high blood sugar levels (hyperglycemia), caused by insulin malfunctioning, deficient insulin secretion, or both." (PMID 35002743, 2021). "Diabetes mellitus is a chronic metabolic condition characterized by hyperglycemia caused primarily by insulin resistance, inadequate insulin production, or both." (PMID 34206641, 2021). "Insulin therapy in AMI is associated with a 30% relative risk reduction in 1‐year mortality, as was demonstrated by Diabetes and Insulin‐Glucose infusion in Acute Myocardial Infarction (DIGAMI) trial." (PMID 33463901, 2021). "T1D is a complex and chronic disorder of the endocrine system, in which the body attacks its own insulin-producing Beta cells, necessitating the need for insulin injection." (PMID 38774890, 2021). "In fact, impaired insulin secretion along with inadequate peripheral tissue response to insulin is the main and direct cause of diabetes through dysregulating of energy and glucose metabolism." (PMID 33892738, 2021). "Diabetes mellitus is one of the five leading causes of death in the world, characterized by impaired insulin secretion, insulin activity, or both, and is divided into two categories: type 1 diabetes and type 2 diabetes." (PMID 33546744, 2021). "The categorical variables insulin treatment at baseline and dyslipidemia were also negatively associated with diabetes remission." (PMID 33990366, 2021). "Diabetes mellitus is a metabolic disease caused by insufficient insulin secretion and/or insulin resistance, leading to high blood glucose levels." (PMID 34885816, 2021).
diabetes (continued). "This pathway is associated with low insulin production and is an indicator of disruptions in glucose metabolism leading to diabetes, a disease that tends to emerge in stunted individuals." (PMID 34565452, 2021). "Insulin-treated women having family history of diabetes represented the subgroup with the highest PPD risk (OR 5.57, 95% CI 3.60–8.63) compared to the reference class (women on diet with pre-pregnancy BMI < = 28.1 kg/m2)." (PMID 33842997, 2021). "Insufficient pancreatic β-cell or insulin-producing β-cell are implicated in all types of diabetes mellitus." (PMID 34262457, 2021). "Diabetes mellitus is a metabolic disease likely caused by defective insulin secretion and more likely by oxidative injury and dysfunction of β cells." (PMID 33661932, 2021). "mAb125, from which the anti-insulin 125Tg BCR is derived, harbors two CDR2 mutations in VH125 that confer modest rodent insulin recognition (8 × 106 M−1), yet 125Tg B cells support diabetes in NOD mice." (PMID 33418839, 2021). "Together, these early works identified loss of insulin as a key driver of the hyperglycemia in diabetes mellitus and led to a new stage of research focused on understanding the pathogenic factors that lead to insulin-deficiency and diabetes." (PMID 34822454, 2021). "Diabetes is linked to changes in cerebrovascular function, oxidative stress, AGEs, and insulin signaling system impairments." (PMID 33668979, 2021). "Diabetes mellitus is a complex metabolic disorder caused primarily due to the disturbed insulin release or insulin sensitivity." (PMID 35052591, 2021). "As patients with PTDM share common metabolic CVD risk factors with those with pre-transplant diabetes, the mechanistic pathways of abnormalities in insulin sensitivity and insulin secretion resulting in adverse CVD outcomes are likely to be similar." (PMID 36994340, 2021). "Diabetes is defined by a loss of control of blood glucose regulation, caused by an inability of insulin secretion to sufficiently meet the demand to clear blood glucose." (PMID 34159399, 2021). "The cited study reported that myristic acid ameliorates the risk of diabetes progression and/or development in vivo by improving insulin sensitivity." (PMID 34961044, 2021). "Mice with a selective disruption of the Pdx1 gene in β-cells develop diabetes associated with a reduction in insulin production and GLUT2 expression." (PMID 34638652, 2021). "In terms of diabetes, factors such as duration, insulin use, weight loss, and age have been shown to contribute to the likelihood of remission." (PMID 34723954, 2021). "The association of genetic polymorphisms in sex hormone biosynthesis and action with insulin sensitivity and diabetes mellitus in women at midlife." (PMID 34644788, 2021). "Few studies have evaluated the correlation of diet quality and fasting blood sugar and insulin, and most of them have evaluated the correlation of the risk of diabetes and scores of diet quality indices." (PMID 33747570, 2021). "In a randomized controlled study of overweight or obese patients with type 2 diabetes, weight loss was shown to lead to improved insulin response and diabetes remission." (PMID 34579047, 2021). "In our research, heart failure, chronic kidney disease and diabetes mellitus treated with insulin injections on admission also contributed to increased risk for altered states of consciousness during hospitalization." (PMID 34279458, 2021). "Many studies on STZ-induced diabetes in the animals have indicated a decrement in pancreatic enzyme levels, which were attributed to the insulin reduction caused by β-cell damage, which was reversible upon insulin administration." (PMID 33880360, 2021). "Deficiency of insulin or the cell’s failure to respond to insulin results in hyperglycemia, which is a key feature of diabetes." (PMID 33541316, 2021).
diabetes (continued). "Insulin is a hypoglycemic peptide hormone that plays a major role in maintaining proper glucose metabolism and is tightly linked to pathologies such as diabetes mellitus." (PMID 34944640, 2021). "Zinc-binding metalloprotease Insulin Degrading Enzyme (IDE) binds to substrates insulin and amyloid-β with more affinity for insulin, predictable to be associated with the interconnection between diabetes and AD." (PMID 34183987, 2021). "Between 5 and 10% of diabetics are type 1, characterized by an autoimmune process with genetic predispositions and potential environmental factors that results in destruction of insulin-producing Beta cells in the pancreas." (PMID 34458216, 2021). "This is not universal though with published studies showing that the higher acquisition costs of long-acting insulin analogues can be fully or partially offset by savings from averted costs of hypoglycaemia and other diabetes-associated complications." (PMID 34676266, 2021). "Diabetes mellitus (DM) is an endocrine, metabolic disorder characterized by elevated blood glucose levels caused by limited insulin production or peripheral resistance to its actions." (PMID 34712528, 2021). "Diabetes mellitus is a metabolic disease characterized by hyperglycemia resulting from deficiency in insulin secretory capacity, insulin action or both." (PMID 33829033, 2021). "Diabetes mellitus is caused by breakdown of blood glucose homeostasis, which is maintained by an exquisite balance between insulin and glucagon produced respectively by pancreatic beta cells and alpha cells." (PMID 33428669, 2021). "In a case report, a point mutation of furin at the insulin proreceptor-processing site was associated with diabetes." (PMID 33429337, 2021). "Large prospective studies and meta-analyses have concluded that anti-TNF therapy improved hyperglycemia or insulin sensitivity and, importantly, reduced lifetime risk of diabetes." (PMID 34616762, 2021). "In particular, diabetes medications, including sulfonylurea and insulin, were nominally associated with all four DNAm age acceleration measures." (PMID 34083497, 2021). "Diabetes mellitus is a common metabolic disorder characterized by absolute or relative deficiencies in insulin secretion and/or insulin action associated with chronic hyperglycemia and with an increased risk of microvascular and macrovascular disease." (PMID 33034919, 2021). "When the incretin effect is weakened, insulin release decreases, causing postprandial blood sugar to rise and blood sugar fluctuations to increase, eventually leading to diabetes." (PMID 34751249, 2021). "There is an increased risk of prolonged QTc in patients with prolonged diabetes, female sex, insulin therapy, BMI, and systolic pressure." (PMID 34692349, 2021). "We therefore recommend that high-risk patients (i.e. patients with higher FPG and those who require insulin treatment during pregnancy) be informed about their individual risk of developing diabetes." (PMID 33021758, 2021). "Studies have shown the association of permanent changes in pancreatic β-cell function or tissue sensitivity to insulin early in life and nutritional changes with insulin resistance and the risk of future diabetes." (PMID 34975761, 2021). "Daily management of diabetes, periprandial decisions, physical activity, insulin therapy itself—all these create the risk of hypoglycemia and its consequences." (PMID 34070638, 2021). "Diabetes or diabetes mellitus is a metabolic disorder causinghigh blood sugar owing to either inadequate production of insulinor incompetent cell response to insulin." (PMID 34043907, 2021). "Both groups were similar in terms of the BMI, cardiovascular risk factors, diabetes duration, insulin use, the degree of metabolic control, and the presence of micro- and macroangiopathic complications." (PMID 34442342, 2021).
diabetes (continued). "It is important to highlight that, in the multivariate analysis, treatment of diabetes was the risk factor that was most strongly associated with DR, especially in patients receiving insulin." (PMID 35010958, 2021). "The authors conclude that neonatal diabetes-associated INS-mutations lead to defective β cell mass expansion, contributing to neonatal diabetes development." (PMID 34295307, 2021). "Recent study showed that blocking OxLDL by its antibody significantly improved insulin sensitivity and reduced plasma level of cholesterol and triglyceride in obese Rhesus Macaques, pointing out the association between OxLDL and diabetes." (PMID 34578896, 2021). "Vitamin K consumption has been linked to insulin sensitivity, glucose tolerance, and thereby diabetes in many studies." (PMID 33924088, 2021). "Insulin is the only hormone that decreases blood sugar, and the pathophysiology of diabetes can be classified into two main groups: insulin deficiency and increased insulin resistance." (PMID 34887872, 2021). "T2D is characterized by a transient condition called pre-diabetes and a decrease in glucose tolerance/insulin sensitivity that causes abnormal glucose homeostasis." (PMID 34574159, 2021). "T1D accounts for 10% of all people diagnosed with diabetes and is caused by autoimmune destruction of pancreatic insulin-producing beta-cells." (PMID 34944607, 2021). "Nonetheless, the question remains as to why monocytes were not increased as a consequence of the increased epinephrine in mice with hepatocyte-specific G6pc1 deficiency, similar to effects of insulin injections in patients with diabetes." (PMID 34091064, 2021). "Studies on rat model (BBZDR/Wor) with diabetes revealed loss of neurons, neural dystrophy, elevated amyloid levels, and tau hyperphosphorylation with decreased expression of insulin and IGF-1 receptors." (PMID 34183987, 2021). "Diabetes mellitus (DM) is a complex chronic illness that occurs due to insulin secretion deficiencies associated with high blood glucose levels." (PMID 34065175, 2021). "Second, misfolded proinsulin can abnormally interact with co-expressed proinsulin-WT via proinsulin dimerization interface, impairing folding and the ER export of proinsulin-WT, decreasing insulin production, and leading to insulin-deficient diabetes." (PMID 35069438, 2021). "Here we discuss the possibilities of using hPSCs to model the impact of diabetes-associated genetic variants on the physiology of the beta cell, focusing on the molecular mechanisms impairing insulin secretion." (PMID 33828531, 2021). "This study provides novel pathophysiologic insights and is an important resource for understanding adipocyte functions in insulin-deficient diabetes." (PMID 34888323, 2021). "The current study demonstrates the genetic susceptibility for impaired insulin secretion and sensitivity, as well as for the development of diabetes in women with a history of GDM." (PMID 34801028, 2021). "Diabetes mellitus is caused by two factors: a decrease in insulin production in the pancreatic islet, and a decrease in insulin sensitivity in the target tissues, such as muscle, fat, and liver." (PMID 33916424, 2021). "At 6 months, 4 patients (3.8%) still feel tired, 2 (1.9%) had peripheral neuropathy, 5 (4.8%) had diabetes requiring insulin treatment, and 4 (3.8%) complained of hair loss." (PMID 34414665, 2021). "There are other studies, however, that show an insulin-independent association with diabetes and breast density." (PMID 33803201, 2021). "Type 1 diabetes (T1D) is one subtype of diabetes that is caused by autoimmune attacks to self‐insulin‐producing β‐cells." (PMID 34026440, 2021). "Diabetes also reduced the level of GLUT4 (encoded by SLC2A4) that functions as an insulin-regulated facilitative glucose transporter in the heart by 70%." (PMID 34616362, 2021).
diabetes (continued). "Hepatic Sam68 expression is also upregulated in patients with diabetes and in two diabetic mouse models, while hepatocyte-specific Sam68 deficiencies alleviate diabetic hyperglycemia and improves insulin sensitivity in mice." (PMID 34099657, 2021). "Diabetes is defined clinically by the presence of hyperglycemia, which is largely caused by insufficient insulin release from pancreatic β cells." (PMID 34822454, 2021). "All these mechanisms would cause disturbances in insulin-glucose control and increase the risk of diabetes." (PMID 33672896, 2021). "STZ is commonly used as diabetes inducing agent in experimental animals due to its capability of specific necrosis induction of pancreatic β-cells that consequences in loss of insulin secretion, leading to hyperglycaemia and diabetic complications." (PMID 33670981, 2021). "Definition of diabetes according to the American Diabetes Association (ADA) is a group of metabolic diseases characterized by hyperglycemia resulting in either deficiency of insulin secretion, insulin action, or both." (PMID 33747462, 2021). "The monogenic form of diabetes is associated with a single gene defect, most often related to insulin secretion pathways." (PMID 34944640, 2021). "For both type 1 (T1D) and type 2 (T2D) diabetes, a clear role for absolute deficiency or insufficiency in insulin has been established." (PMID 33460647, 2021). "Insufficient insulin secretion or inadequate reaction between cell receptors and insulin causes glucose metabolic abnormalities that result in diabetes mellitus." (PMID 36338772, 2021). "The main cause of hypoglycemia in diabetes is glucose lowering therapy: exogenous insulin or insulin secretagogues, such as sulfonylureas." (PMID 34638984, 2021). "The purpose of this study was to determine the basal regulation of adult retinal IR activity and how it is affected by insulin-deficient diabetes." (PMID 33915127, 2021). "The proliferation of pancreatic islet β cells is regulated by the cell cycle process, and decreased insulin secretion caused by reduced β cell proliferation is the main cause of diabetes." (PMID 34272768, 2021). "Although not all miRNA-gene interactions in TarBase were reported from diabetes-related tissues, the finding suggests that diagnostic miRNAs play important roles within the insulin signaling pathway." (PMID 35008723, 2021). "Insulin balls, localized insulin amyloids formed at subcutaneous insulin-injection sites in patients with diabetes, cause poor glycemic control owing to impairments in insulin absorption." (PMID 33767265, 2021). "Duration of diabetes, glycemic control, use of insulin, age, and postoperative weight loss have all been shown to be associated with the chance of diabetes remission." (PMID 34723954, 2021). "On the basis of these observations, the activation of glycogen deposition emerges as a potential therapeutic target for the treatment of insulin-deficient diabetes." (PMID 33667544, 2021). "Based on literature and our findings, we suggest that the primary cause of itch is prolonged poor diabetes control with altered glucose and insulin levels, subsequently causing skin dryness and small-fibre neuropathy in long-lasting DM2." (PMID 34943248, 2021). "This is in line with recent in vivo evidence that a novel T2D cis-gene previously mapped using the same method, ABCC5, was functionally implicated in diabetes by improving insulin sensitivity and reducing fat mass when knocked-out in mice." (PMID 34456865, 2021). "Modern medicine believes that diabetes is an endocrine and metabolic disease characterized by glucose metabolism disorder caused by relative or absolute insufficiency of insulin secretion in the body." (PMID 34724560, 2021). "In 2002, CHOP deficiency was found to delay the onset of diabetes in Akita mice that exhibit insulin misfolding and β-cell ER stress." (PMID 34822454, 2021).